SIGMAR1 (sigma non-opioid intracellular receptor 1)
Diseases named in the same sentence as SIGMAR1 in open-access papers (continued):
Sharing a sentence is not in itself a finding about the gene and the disease.
neurodegenerative disease (22 papers, 2013 to 2025). A disorder of the central nervous system characterized by gradual and progressive loss of neural tissue and neurologic function. "Here, we summarize the different neurodegenerative diseases associated with the dysfunction of Sigmar1." (PMID 34305655, 2021). "SIGMAR1 receptors are abundantly expressed in the brain and SIGMAR1 agonists such as blarcamesine have demonstrated effects in slowing neurodegenerative diseases." (PMID 39800452, 2025). "Activation of SIGMAR1 exerts neuroprotective functions demonstrated in numerous models of neurodegenerative diseases, including ALS-FTD." (PMID 35507432, 2023). "On the other hand, overexpression of SIGMAR1 in HEK 293 cells caused a decrease in the expression of the proinflammatory cytokine IL-8, which production increases during neurodegenerative diseases." (PMID 36614266, 2023). "Sigmar1 knockout mice are characterized by numerous disorders typical for neurodegenerative diseases." (PMID 36614266, 2023). "This makes Sigmar1 a possible target in treating pathologies where modulating Sigmar1 activity could be used as a therapeutic approach in the treatment of neurodegenerative diseases." (PMID 34305655, 2021). "Overall, Sigmar1 activation has shown protective effects in different neurodegenerative diseases (AD, HD, PD) through the involvement of different cellular pathway modulation, including mitochondrial function regulation, autophagy, calcium homeostasis regulation, and chaperone function." (PMID 34305655, 2021). "Broadly, Sigmar1 activation using ligands elicit potent neuroprotective effects, promotes neuronal survival, and restores neuronal plasticity to slow disease progression, whereas dysfunction in Sigmar1 may worsen the progression of neurodegenerative diseases." (PMID 34305655, 2021). "This antagonism by Sigmar1 on VDCC and calcium current were used to treat painful neuropathies, reduce the unwanted increase in vascular permeability and angiogenesis, target excitotoxicity-induced neurodegenerative disease, and confer neuroprotection." (PMID 34305655, 2021).
infection (7 papers, 2017 to 2024). The state of being infected such as from the introduction of a foreign agent such as serum, vaccine, antigenic substance or organism. "We generated replication-deficient FLAG-tagged Sigmar1 adenovirus and confirmed expression levels in NRCs by increasing concentrations of adenoviral infections (1–20 multiplicity of infection (MOI))." (PMID 28667101, 2017).
cardiovascular diseases (5 papers, 2021 to 2024). "Multiple pre-clinical studies have suggested generating novel protective therapeutic options for renal and cardiovascular diseases through Sigmar1 activation." (PMID 39200372, 2024). "Sigmar1 is a ubiquitously expressed, multifunctional protein known for its cardioprotective roles in cardiovascular diseases." (PMID 38742156, 2024). "Previous studies have demonstrated the advantageous impacts of Sigmar1 on cardiac function and have identified this receptor as a potential target for the prevention and treatment of cardiovascular disease." (PMID 37893138, 2023). "The sigma-1 receptor (Sigmar1) is a ligand-dependent molecular chaperone that is postulated to be involved in various processes related to cardiovascular disease." (PMID 37893138, 2023).
infectious disease (1 paper, 2025). A disorder directly resulting from the presence and activity of a microbial, viral, or parasitic agent in humans. "Recently, it has been suggested that Sigmar1 may play a role in peripheral diseases beyond cardiovascular conditions, and attempts have been made to apply Sigmar1 ligands to peripheral diseases, such as cancer, infectious diseases, and respiratory diseases." (PMID 40005987, 2025).
SIGMAR1 also shares sentences with these, for which no sentence is quoted: Alzheimer disease (19 papers); neurological disorders (9); Cerebral ischemia (6); psychiatric diseases (6); cocaine addiction (5); ischemic stroke (5); melanoma (5); Dravet syndrome (4); motor neuron disease (4); autosomal recessive dHMN (3); dementia (3); glioblastoma (3); glioma (3); Parkinsonism (3); alcoholism (2); amnesia (2); brain tumor (2); central nervous system diseases (2); chronic kidney disease (2); cognition disorders (2); distal spinal muscular atrophy (2); injury (2); motor neuron degeneration (2); myocardial ischemia (2); post-traumatic stress disorder (2); prostate adenocarcinoma (2); retinal disease (2); retinopathy (2); Seizure (2); small cell lung carcinoma (2).
A further 66 diseases each share a sentence with SIGMAR1 in 2 papers or fewer.